TGFB1 (transforming growth factor beta 1)
Diseases named in the same sentence as TGFB1 in open-access papers (continued):
Sharing a sentence is not in itself a finding about the gene and the disease.
renal fibrosis (continued). "It is widely accepted that although many factors are implicated in the cellular dysfunction observed in diabetes mellitus, high glucose-induced TGFβ1 and its downstream signalling play an essential role in the development of renal fibrosis, indeed in all forms of nephropathy." (PMID 23991195, 2013). "Mice with increased plasma TGFβ1 levels displayed enhanced renal fibrosis." (PMID 22879939, 2012). "To confirm whether Gal3 promotes renal fibrosis mainly through the regulation of the TGFβ1 signaling pathway, we treated renal fibroblasts with Gal3 and TGFβ1, along with either the TGFBR2 inhibitor (LY2109761) or the TGFβ1 signaling pathway inhibitor (PD169316)." (PMID 40799164, 2025). "Our study observed a concurrent upregulation of all three isoforms and interestingly a relatively higher upregulation of TGFβ2 than TGFβ1/TGFβ3 in both tissues and cells, possibly suggesting that TGFβ2 may critically contribute to XLAS associated renal fibrosis." (PMID 40075271, 2025). "Furthermore, emodin, rhein, and crocetin, which are also present in QDTS, have been reported to have beneficial effects in DN, such as enhancing the expression of transforming growth factor-beta 1 (TGF-β1), reducing renal fibrosis, regulating metabolism, and mitigating oxidative stress." (PMID 38223704, 2024). "Since DNA-PKcs is involved in the phosphorylation of TAF7 in renal fibrosis, we examined whether TAF7 deficiency may affect the dedifferentiation of renal epithelial cells or the activation and proliferation of interstitial fibroblasts induced by TGFβ1." (PMID 36906617, 2023). "Similarly, it is unclear whether TGFβ1 could control α-SMA expression through regulating Id2 in a human epithelial cell type relevant to renal fibrosis." (PMID 23320068, 2013). "We found that Gal3 deletion significantly mitigated renal fibrosis in DKD mice and concurrently reduced renal Tgfb1 expression." (PMID 40799164, 2025). "Pro‐fibrotic mediators (including transforming growth factor beta‐1 [TGFβ‐1]), are central components of the SASP and efficacious drivers of renal fibrosis." (PMID 38995865, 2025). "Fibrosis markers, including transforming growth factor-beta 1 (TGF-beta 1) and various types of collagens, are involved in renal fibrosis, a common pathway in CKD progression." (PMID 39463626, 2024). "Inflammatory cells release transforming growth factor beta 1 (TGF-ß1), which stimulates the synthesis of ECM proteins, contributing to renal fibrosis." (PMID 38341510, 2024). "In accordance with this study, recent studies have also found that ADSC treatment significantly reduces renal fibrosis and reduces renal levels of mRNA COL1A1, TGFB1, CTGF, and ACTA2." (PMID 39309193, 2024). "BNIP3 deficiency increased the production of mitochondrial ROS, the NLRP3 inflammasome, and αSMA and TGFβ1 expression, indicating the protective role of BNIP3-mediated mitophagy in renal fibrosis." (PMID 36928344, 2023). "Transforming growth factor-beta 1 (TGF-β1) is a cytokine that is critical for the progression of CKD and its upregulation can lead to progressive renal fibrosis." (PMID 35324842, 2022). "Through an increase in the level of lysosomal protein degradation, LM49 reversed the TGFβ1-induced imbalance between ECM production and ECM degradation, which presents a promising strategy for renal fibrosis therapy." (PMID 36225562, 2022). "Renal fibrosis is characterized by the abnormal accumulation of ECM, with TGFβ1 as the central mediator, inducing increased matrix protein synthesis and inhibiting matrix degradation." (PMID 34645813, 2021). "Transforming growth factor beta 1 (TGF-β1) stimulates overexpression of extracellular matrix proteins, such as collagen IV, and is the key regulator of renal fibrosis." (PMID 34573096, 2021). "As two key modulators of matrix accumulation, TGFβ1, and PAI-1 play an important role in renal fibrosis." (PMID 32478392, 2020).
renal fibrosis (continued). "MiR-133b and miR-199b inhibition suppresses TGFβ1-induced EMT and renal fibrosis by targeting SIRT1 in DN." (PMID 31631065, 2019). "The aim of this study was to evaluate the role of angiotensin II (AT-II) and its main mediator, transforming growth factor beta 1 (TGF-β1), in the development of feline renal fibrosis." (PMID 30345862, 2019). "Previous studies described that TGFβ1 enhanced α-SMA, COL1A1, COL3A1, and CTGF levels to drive renal fibrosis mediated by the miR-433." (PMID 30536131, 2019). "IL-6 invades the adipose tissue and influences transforming growth factor – beta 1 (TGF-β1) receptor trafficking, leading to renal fibrosis." (PMID 29454330, 2018). "However, whether the increase in TGFβ1 expression was caused by stimulation of HMCs with pGSN, and whether it could activate the downstream Smads proteins that can cause renal fibrosis, were not clear." (PMID 28208683, 2017). "T869C gene polymorphism of TGFβ1 changes properties, pattern and binding stability of TGFβ1 signal peptide with SRP and translocon that contributes to the production of urinary TGFβ1 and renal fibrosis in lupus nephritis." (PMID 25279306, 2014). "Renal fibrosis is the principal feature of ESRD, and TGFβ1 are assumed to have a significant role in the profibrotic effect." (PMID 25279306, 2014). "Transforming growth factor-beta 1 (TGF-β1), which shows enhanced expression in human fibrotic kidneys and in animal models of renal fibrosis, promotes renal fibrosis through the activation of interstitial fibroblasts and acts as a potent inducer of EMT." (PMID 24883308, 2014). "Opposing regulators of epithelial/mesenchymal phenotype in renal proximal tubule epithelial cells (PTEC), TGFβ1 and BMP7 also have counter-regulatory effects in models of renal fibrosis." (PMID 23320068, 2013). "Affected kidneys showed an adaptive response that involves the appearance of α-smooth muscle actin (SMA) positive myofibroblasts, expanded TGFβ1 and CTGF expression, and the development of limited renal fibrosis." (PMID 24023768, 2013). "In contrast to TGFβ1, BMP 7 the other member of TGF family has been shown to have anti-fibrotic effect in both in vivo and in vitro models of renal fibrosis." (PMID 23320068, 2013). "Since TGFβ1 is primarily released from extracellular Pro‐TGFβ1, we hypothesized that Gal3 may also increase renal TGFβ1 levels in DKD by slowing Pro‐TGFβ1 degradation, thus contributing to renal fibrosis." (PMID 40799164, 2025). "Collectively, increased prorenin expression caused by the long-term consumption of microcystin-LR may initiate a process that influences renal fibrosis and abnormal renal function by regulating the expression levels of PRR, TGFβ1, and α-SMA." (PMID 39195649, 2024). "Consequently, FABP5P3 reversed TGFβ1-induced FAO suppression in proximal tubular epithelial cells and ultimately alleviated renal fibrosis." (PMID 38002328, 2023). "In UUO model group, Tgfβ1/Smad2/3 pathway, Wnt4/β-Catenin pathway, and NGFR/NF-κB pathway were activated, which led to inflammatory response and accelerated cell proliferation, thus promoting the progression of renal fibrosis." (PMID 37198665, 2023). "In kidney, FABP5P3 could improve TGFβ1-stimulated deregulation of fatty acid oxidation (FAO) and renal fibrosis." (PMID 38002328, 2023). "Therefore, our study demonstrated that RSGB suppressed the inflammatory response and cell cycle by inhibiting the Tgfβ1/Smad2/3 pathway, Wnt4/β-Catenin pathway and NGFR/NF-κB pathway, thereby exerting an anti-renal fibrosis effect." (PMID 37198665, 2023). "NRK52E cells were treated with TGFβ1, a fibrosis-inducing cytokine, and with or without β-OHB, a ketone body metabolized by KD, to investigate the mechanism underlying renal fibrosis." (PMID 37032786, 2023).
renal fibrosis (continued). "Furthermore, we demonstrated that renal fibrosis was attenuated by decreasing mitochondrial ROS and NLRP3 inflammasome production and TGFβ1 activation with MitoTEMPO, a selective mitochondrial-targeted antioxidant, and MCC950, a specific NLRP3 inhibitor." (PMID 36928344, 2023). "Renal fibrosis is essential for CKD development and progression, and the major mediator is TGFβ1." (PMID 34645813, 2021). "Previous studies also showed that TGFβ1 could be induced in PTCs in CKD and in aging kidney, which plays a role in renal fibrosis." (PMID 34867480, 2021). "Although, we did not detect renal fibrosis, the obese mice exhibited a significant elevation of Tgfb1 mRNA levels." (PMID 34291592, 2021). "FMT did not prevent the expression of renal fibrosis-related genes (TGFβ1 Transforming Growth Factor beta 1) and inflammatory cytokines (IL-6, Interleukin 6 and TNFα, Tumor Necrosis Factor alpha) in the kidney." (PMID 33255454, 2020). "Moreover, uPIIINP levels also correlated with urinary levels of transforming growth factor beta 1 (TGF-β1), which is commonly used as biomarker for renal fibrosis, assessment in humans and cats." (PMID 33132611, 2020). "TGFβ1/SMAD signaling increases the transcription of α-smooth muscle actin (SMA), fibronectin, collagen I, and vimentin, and decreases E-cadherin expression to promote renal fibrosis." (PMID 32364526, 2020). "Transforming growth factor beta 1 is a key mediator of inflammation and fibrosis, widely described as involved in PMF pathogenesis and able to upregulate miR‐382‐5p in renal fibrosis." (PMID 30259659, 2018). "Despite TGFβ1 being recognised as a mediator of renal fibrosis and functional decline role in diabetic nephropathy, the renal interaction between Nox 4 and TGFβ1 is not well characterised." (PMID 23991195, 2013). "Among the various mediators of renal fibrosis, transforming growth factor-β1 (TGFβ1) is a representative molecule that plays a central role in this process, particularly by activating the promoter region of α-smooth muscle actin (α-SMA) in renal fibrosis, resulting in increased α-SMA expression." (PMID 39195649, 2024). "Moreover, hydrogen-rich water has been shown to attenuate renal fibrosis and suppress the epithelial–mesenchymal transition (EMT) process in human kidney proximal tubular epithelial cells (HK-2 cells) by upregulating Sirt1, a molecule modulated by transforming growth factor beta 1 (TGF-β1)." (PMID 38790620, 2024). "In addition, overexpression of latent TGFβ1 was shown to decrease both SMAD2/3 activation (transcription factors of canonical TGFβ1 signaling) and the number of myofibroblasts, which is in line with findings that SMAD3 knockout mice are protected from renal fibrosis." (PMID 29651290, 2018).
lung carcinoma (1,064 papers, 2000 to 2026). "This study systematically evaluated the potential causal relationship between three key inflammatory factors (CDKL1, CXCL8 and TGFB1) and the risk of non‐small cell lung cancer (NSCLC) using Mendelian randomisation (MR) methodology." (PMID 40682474, 2025). "In vitro, Chidamide treatment has been shown to attenuate TGFβ1-induced loss of E-cadherin expression in lung cancer cells." (PMID 39409910, 2024). "Overall, these results revealed that the role of cooperation between PGC1α and FOXA1 on the transcription of ID1 is functionally linked to TGFβ1-mediated EMT in lung cancer cells." (PMID 35897813, 2022). "Transforming growth factor beta 1 (TGFβ1), associated with inflammation and lung cancer risk and the smoking-related differentially methylated gene Aryl-hydrocarbon receptor repressor (AHRR) are likewise modifiers of CF lung disease." (PMID 34415821, 2022). "As such, additional studies are needed to validate this finding and to investigate the mechanisms by which TGFβ1 polymorphisms influence the course of lung cancer development and progression." (PMID 23840350, 2013). "The evidence from a GWA study supports that the TGFB1 gene is associated with tobacco-induced lung cancer." (PMID 23094028, 2012). "The SNPs rs1800469 and rs2241712 in the promoter of the TGFB1 gene on chromosome 19 were associated with chronic obstructive pulmonary disease and lung cancer in smokers in previous studies." (PMID 23094028, 2012). "Previous authors reported that the SNPs rs1800469 and rs2241712 in the promoter of the TGFB1 gene are associated with chronic obstructive pulmonary disease and lung cancer in cigarette smokers." (PMID 23094028, 2012). "PM10 induces overexpression of TGFB1 and genes involved in the activation of the epithelial–mesenchymal transition in lung cancer cell line A549, predisposing cells to the acquisition of an invasive phenotype, a hallmark necessary during the carcinogenic process." (PMID 34884446, 2021). "rs2241714 is located in the promotor of the TGFB1 gene and it is associated with lung cancer." (PMID 29228579, 2017). "For instance, changes in circulating levels of epidermal growth factor (EGF) and transforming growth factor beta 1 (TGFβ1), due to functional genetic variants, could influence the risk to develop prostate and lung cancer, respectively." (PMID 23233863, 2012). "Most significantly, elevated serum TGFβ1 levels were correlated with an increased risk of fibrosis in breast and lung cancer patients and a comparison of the genotypes of unaffected and affected patients has been genetically associated with functional polymorphisms in the TGFβ1 gene." (PMID 17325707, 2007). "We also assessed expression changes for genes that change during lung cancer progression, including Cxcl1, Tgfa, and Tgfb1." (PMID 39782689, 2025). "In lung cancer, the transition of fibroblasts into CAFs is mediated by the profibrotic cytokine transforming growth factor beta 1 (TGF-β1), produced from epithelial cells, much like other wound healing processes." (PMID 39403603, 2024). "Next, we analysed the RNA expression levels of the TGFβ target genes p21, PAI1, SMAD7, and TGFB1 following SHP099 treatment in KRAS mutant lung cancer cell lines." (PMID 38102334, 2023). "For instance, polysaccharides obtained from PL were investigated for early metastasis of lung cancer and it was found that they suppressed transforming growth factor-beta 1 (TGF-β1)-induced epithelial-to-mesenchymal transition in A549 cells." (PMID 36840285, 2023). "Several studies have also demonstrated that transforming growth factor beta 1 (TGFβ1) enhances human chondrosarcoma and lung cancer cells’ migration through the PI3K/Akt signalling pathway." (PMID 38002001, 2023). "CM from NSCLC CAFs induces EMT, acquisition of cancer stem cell-like qualities in vitro, and enhanced tumor formation in vivo in lung cancer cell lines, mediated through an increased expression of TGFβ1, as compared to NFs." (PMID 37046676, 2023).
lung carcinoma (continued). "In a previous study in our laboratory, changes in many different DUSP proteins were observed after the induction of nonsmall cell lung cancer cells (A549) with TGFβ1, and a significant decrease in DUSP4 and DUSP13 was observed." (PMID 37476896, 2023). "In this study, Pc-Ex, which contains emodin as a major component, sufficiently suppressed the PTHLH mRNA and PTHrP expression levels in lung cancer cells stimulated with TGFβ1 by inhibiting the interaction between TCF4 and TWIST1." (PMID 35406121, 2022). "TGFB1 is a ligand secreted by several cells in the tumor microenvironment and plays a critical role in lung carcinoma." (PMID 35137551, 2022). "Initially, we measured PGC1α in the absence or presence of TGFβ1, and decreased PGC1α mRNA was observed in TGFβ1-treated A549, H358, H1666, and Calu-1 lung cancer cells." (PMID 35897813, 2022). "Through bioinformatic analysis of the GSE114761 dataset increased PTHLH mRNA levels were found in TGFβ1-treated many types of lung cancer cells." (PMID 35406121, 2022). "TGFβ-1 characteristics in early stage lung cancer of this study was represented with unchanged steady levels of this marker in NNK group compared to control." (PMID 36518397, 2022). "The interaction between TCF4 and TWIST1 upregulated PTHLH expression in lung cancer cells in response to TGFβ1 stimulation." (PMID 35406121, 2022). "Consistent with the findings of previous studies, this study demonstrated that the expression of PTHLH was upregulated in response to TGFβ1 signalling in various lung cancer cell lines." (PMID 35406121, 2022). "In the present study, overexpression of TGFβ1 in CAFs appeared to enhance the apoptosis of lung cancer cells after radiotherapy." (PMID 34095135, 2021). "Given the convergence of Wnt and transforming growth factor-β (TGFβ) signalling, we examined the effects of a small-molecule TNIK inhibitor (named NCB-0846) on the TGFβ1-induced EMT of lung cancer cells." (PMID 33244122, 2021). "TGFβ1/integrin β3 axis has been proposed as an anticipating target for combination therapy in EGFR-mutant lung cancer." (PMID 35153741, 2021). "The present study focused on TGFβ1 in CAFs and its growth-promoting activity in lung cancer cells in vivo and in vitro." (PMID 34095135, 2021). "S1P mediated EMT by regulating the autocrine production of TGFβ1, which contributed to a fibrotic response in A549 lung cancer cells." (PMID 31822964, 2020). "Here, we show that snc886-3p is also associated with Argonaute in lung cell line WI-38, which is in agreement with the proposed microRNA identity of hsa-miR-886-3p (here snc886-3p) acting through direct repression of PLK1 and TGFB1 in lung cancer." (PMID 32093270, 2020). "It has been reported that NE can trigger epithelial mesenchymal transition in lung cancer cells and promote the invasion and metastasis of lung cancer by regulating the transforming growth factor-beta 1 signaling pathway." (PMID 33178600, 2020). "The results show that the TGFβ-EMT signature successfully discriminated lung cancer cell lines capable of undergoing EMT in response to TGFβ-1 and predicts MFS in lung adenocarcinomas." (PMID 30783512, 2019). "It is also reported that the induction of EMT by TGFβ-1 increases stemness properties in primary lung cancer cells." (PMID 31119150, 2019). "We demonstrate, through bioinformatics analysis, that this signature can identify lung cancer cell lines capable of undergoing EMT in response to TGFβ-1, and is transferable to human tumors." (PMID 30783512, 2019). "Geraniin inhibited transforming growth factor beta-1 (TGF-β-1)-induced EMT in lung cancer cells by increasing the expression of E-cadherin and inhibiting expression of Snail, a transcription factor crucial for induction of EMT." (PMID 31766399, 2019). "Consistent with the co-expression of LINC00261/FOXA2 in lung cancer samples, TGFβ1 also induced a significant suppression of FOXA2." (PMID 30597925, 2018).